RBM26 (RNA binding motif protein 26)
Description:
May be involved in the turnover of nuclear polyadenylated (pA+) RNA.
Synonyms: C13orf10; PRO1777; SE70-2; FLJ20957; ZC3H17; ARRS2; PPP1R132
Tractability: PROTAC: UniProt records ubiquitination sites on it; ubiquitination databases record sites on it; its protein half-life has been measured.
Gene: Protein-coding gene on chromosome 13 (79,311,824 to 79,406,477, reverse strand). Ensembl gene ENSG00000139746.
Subcellular location (Human Protein Atlas): Nuclear speckles
Pathways (Reactome):
Metabolism of RNA: Nuclear RNA decay
Gene Ontology:
Molecular function: protein binding; RNA binding; metal ion binding; nucleic acid binding
Biological process: RNA catabolic process
Cellular component: nucleoplasm; nucleus
Genetic constraint (gnomAD): Loss-of-function variants: 18 observed, 63.92 expected, observed/expected ratio (o/e) 0.28, 90% interval 0.19 to 0.42. The upper end of that interval is the gene's LOEUF score, 0.42, which puts it in group 1 of 6, group 1 being the genes least tolerant of losing a copy. Missense variants: 620 observed, 780.18 expected, observed/expected ratio (o/e) 0.79, 90% interval 0.74 to 0.85. Synonymous variants: 250 observed, 260.32 expected, observed/expected ratio (o/e) 0.96, 90% interval 0.87 to 1.07.
Homologues: Orthologues: chimpanzee RBM26 (100% identical), macaque RBM26 (99% identical), pig RBM26 (99% identical), dog RBM26 (99% identical), rabbit RBM26 (98% identical), rat Rbm26 (97% identical), mouse Rbm26 (97% identical), guinea pig RBM26 (82% identical), tropical clawed frog rbm26 (77% identical), zebrafish rbm26 (69% identical), Drosophila melanogaster swm (31% identical), Caenorhabditis elegans rbm-26 (24% identical). Paralogues in human: RBM27 (47% identical).
Diseases named in the same sentence as RBM26 in open-access papers:
RBM26 is named in the same sentence as 9 diseases in open-access papers, as found by Europe PMC text mining. Sharing a sentence is not in itself a finding about the gene and the disease. The quoted sentences say what the papers report.
schizophrenia (2 papers, 2021 to 2023). A major psychotic disorder characterized by abnormalities in the perception or expression of reality. "RBM26 was associated with schizophrenia in a recent study but only at a level of suggestive significance (P = 3.41 × 10−7)." (PMID 36604601, 2023).
autism (1 paper, 2024). Persistent deficits in social interaction and communication and interaction as well as a markedly restricted repertoire of activity and interest as well as repetitive patterns of behavior. "Autism-associated missense variants in RBM-26 cause a sharp decrease in RBM-26 protein expression along with defects in axon overlap and axon degeneration that occurs during larval development." (PMID 39480871, 2024). "Here, we address this question through the investigation of rbm-26, the Caenorhabditis elegans ortholog of the RBM27 autism candidate gene, which encodes an RNA-binding protein whose role in neurons is unknown." (PMID 39480871, 2024).
developmental delay (1 paper, 2025). "Other candidate AD genes include DACH1, KCTD12, KLF5, and RBM26, all of which have been implicated in syndromic developmental delay, neuropsychiatric traits, or cancer predisposition based on case reports or CNV analyses." (PMID 40978814, 2025).
pancreatic cancer (1 paper, 2024). "Though there is no direct evidence of RBM26 and BP, two previous integrated analysis studies reported that RBM26 acts as immune-related function not only in ASD, but also in non-psychiatric disorder including pancreatic cancer." (PMID 38664746, 2024).
RBM26 also shares sentences with these, for which no sentence is quoted: bipolar disorder (1 paper); breast carcinoma (1); cancer (1); macroglossia (1); psychiatric disorder (1).